KRAS (KRas proto-oncogene, GTPase)
Diseases named in the same sentence as KRAS in open-access papers (continued):
Sharing a sentence is not in itself a finding about the gene and the disease.
tumor (continued). "The mechanism of immune stimulation via KRAS G12C inhibition is unknown, although in a preclinical model, AMG510 treatment was associated with enhanced T cell tumor infiltration and generation of antitumor immunological memory." (PMID 34990404, 2022). "In KRAS(G12C)-addicted tumor models, resistance mechanisms may involve upregulation of RTKs, alternative signaling through PI3K/AKT, and SHP2 dependence, depending on cellular context." (PMID 35510953, 2022). "Subsequent evidence showed that it could result in tumor progression and poor prognosis via activating cell cycle, DNA repair, MYC, and KRAS-associated signaling pathways as well as rendering immune dysregulation." (PMID 36522647, 2022). "Patient L2 had a KRAS-mutated tumor, and patient L4 had a MET-amplified tumor, while no known oncogenic driver alteration was detected for patient L3." (PMID 35511434, 2022). "This indicates that decrease in tumor phospho‐Akt1/2/3 levels is not dependent on KRAS mutation status." (PMID 34919787, 2022). "Once KRAS mutations occur, the hydrolysis of GTP is disrupted and/or nucleotide exchange is enhanced, leading to accumulation of KRAS in the active state and contributing to constitutive stimulation of downstream signaling pathways, thereby promoting tumor cell proliferation and survival." (PMID 35836817, 2022). "These include MSI+ tumours with strong immune infiltration (CMS1), Wnt/beta-catenin proliferative tumours (CMS2) and KRAS mutated and metabolic-deregulated tumours with strong immune exclusion (CMS3), and “mesenchymal” tumours with stromal and innate immune infiltration (CMS4)." (PMID 35740644, 2022). "Our results suggest that a greater ERCC1 expression in mt KRAS tumors might increase platinum resistance in this group of patients, whereas the greater expression of BRCA1 in wt KRAS tumor might be suggestive of the sensitivity of taxanes." (PMID 35877239, 2022). "Consequently, co-targeting of NOP56 and mTOR profoundly enhances KRAS-mutant tumor cell death in vitro and in vivo." (PMID 35039048, 2022). "Another miR might be involved in the regulation of CXCR4, miR-622, which is underexpressed in CRC metastases and has been described as a potential tumor suppressor gene by slowing down KRAS-dependent tumor and metastasis formation in mice." (PMID 35406582, 2022). "The role of KRAS/SMAD4 in the tumor microenvironment has additional value for exploration." (PMID 35887766, 2022). "Different subgroups were assessed for risk scores based on age, gender, tumor location, survival status, T-stage, tumor stage, EGFR mutation status and KRAS mutation status, wherein all the subgroups had significant differences except the tumor location and EGFR mutation status subgroups." (PMID 36498802, 2022). "Other studies have suggested that oncogenic KRAS could damage antigen presentation, resulting in the escape of tumor-infiltrating lymphocytes." (PMID 35571489, 2022). "In addition, resistance to platinum doublets of chemotherapy was found to be greatly increased in patients with a KRAS mutation and low expression of the BRCA1 and TYMS genes in tumor tissue." (PMID 36294786, 2022).
tumor (continued). "We estimated the score of KRAS VAF as a surrogate of constituent tumor purity in samples." (PMID 36266629, 2022). "Mutant KRAS could coordinate a paracrine network to build a tumor microenvironment that is composed of suppressive immune cells, activated stromal cells, and desmoplasia." (PMID 35433680, 2022). "Although specific KRAS-mutant cancer inhibitors were developed recently with a hope of resolving the critical problem in cancer treatment, their applications gain only a partial impact because tumor resistance occurs at a high rate." (PMID 36359850, 2022). "As stated in Methods, all patients with available tumor tissue sample were screened for mutations in the entire series of additional candidate genes (KRAS, ALK, BRAF, MET) regardless of the positive or negative result of the EGFR mutation testing." (PMID 35012520, 2022). "As with the drug-addicted cell line in our model of trametinib resistance, amplification of mutant KRAS in response to AMG-510 may render these tumor cells sensitive to hyperactivation of MAPK signaling if AMG-510 is withdrawn." (PMID 36418460, 2022). "Overall, our results strengthen a now compelling body of evidence that overturns the earlier belief that oncogenic KRAS mutations are fully constitutive – instead, it is clear that KRAS-driven tumours are driven by signalling input to the activated KRAS oncoprotein." (PMID 35971826, 2022). "The mechanism of PI3K pathway mediated resistance to KRAS G12C inhibitors may depend on the tumor type and the degree of cell de-differentiation." (PMID 35267628, 2022). "Additionally, ASOs targeting KRAS also inhibited the tumor growth and invasiveness of HaP-T1 (from the BHP-induced hamster PC model) in a dose-dependent manner, whereas mismatched ASOs were not effective in inhibiting invasion." (PMID 35652096, 2022). "However, there were distinct human breast CNA events identified in the two Tumor samples where one tumor – ‘Tumor1’ was identified as KRAS altered with a chr6 related KRAS amplification, which is a previously noted common event in this tumor model." (PMID 35851387, 2022). "A therapeutic strategy using specific KRAS inhibitors alone might be administered in the near future as first-line treatment for tumors expressing PD-L1 in less than 50% of tumor cells." (PMID 35406400, 2022). ", could be actively internalized by KRAS mutant cancer cells through macropinocytosis, suggesting that macropinocytosis regulation in the tumor setting can be harnessed for the delivery of anticancer therapeutics." (PMID 35154489, 2022). "Our study compared KRAS expression levels between 33 kinds of tumor tissues." (PMID 36330448, 2022). "KRAS plays a certainly critical role in multiple signaling pathways for cell proliferation, differentiation, and survival, being acknowledged as an eminent tumor driver." (PMID 35281897, 2022). "Taken together, these data suggest that elevated levels of KSR1 in human tumours may reduce the efficacy of KRAS inhibitors due to the ability of KSR proteins to activate the MAPK in a RAS‐independent manner." (PMID 35313064, 2022). "Tumor mutational burden (TMB) levels were not significantly different between KRAS wildtype (median TMB = 2.4 mut/Mb) and mutant (median TMB = 1.5 mut/Mb) groups (p = 0.11)." (PMID 36209277, 2022). "Increasing evidence indicated that KRAS signaling could modulate the tumor microenvironment and promote tumor-related immune response, which was also found to be enriched in the low DLL3 expression group." (PMID 36338696, 2022). "Moreover, impeding macropinocytosis and Asn depletion resulted in a prominent tumor growth suppression effect in mutant KRAS CRC cells in vivo." (PMID 36090030, 2022).
tumor (continued). "Importantly, compared to the wild-type counterparts, KRAS-mutant tumors showed higher expression of PD-L1, with the median PD-L1 tumor proportion scores ranging between 30–60% and 5–35% in patients with and without KRAS mutations, respectively." (PMID 36741723, 2022). "Similar to traditional appendix-derived PMP, our patient’s tumor harbored non-targetable mutant KRAS-GNAS co-mutations with ATM mutant positivity." (PMID 35272690, 2022). "Thus, the detection of KRAS mutations within the venous and resection margins of resected PDAC tumours seems valuable." (PMID 35194118, 2022). "Since no KRAS mutation was found in the left lower lobe tumor of patient P07, we went through the following confirmation process." (PMID 34290355, 2022). "It has been proposed that a metabolic shift in the canonical CMS2 tumors possibly due to KRAS mutations and copy number events results in CMS3 tumors whereas the stromal-enriched inflamed tumor microenvironment is the driver for the development of CMS4 tumors from the CMS2 subtype." (PMID 35560039, 2022). "Here, we showed how deltarasin functions to abrogate a mutant KRAS-initiated in vivo inflammatory loop of tumor-derived CCL2 and myeloid-secreted IL-1β by downregulating the IL1R1 expression of KRAS-mutant tumor cells and thereby abolishing their receptivity to myeloid IL-1β signals." (PMID 35327394, 2022). "This constitutively active KRAS protein contributes to cell proliferation, suppression of apoptosis, altered cell metabolism and changes in the tumor microenvironment, which leads to tumorigenesis, tumor maintenance, invasion and metastasis." (PMID 35883626, 2022). "Regarding the establishment of tumor-promoting inflammation, KRAS was shown to be capable of inducing cytokine secretion such as IL-6 and reduced secretion of IFNγ, TNF, and IL-2 by different stromal cell types, e.g., fibroblasts, myoblasts and epithelial cells." (PMID 35965494, 2022). "The KRAS copy number of circulating tumor DNA (ctDNA) was assessed during treatment." (PMID 35734602, 2022). "Moreover, RAS signaling itself promotes reactive oxygen species generation, so redox regulation is highly relevant for KRAS-driven tumor growth and treatment." (PMID 35753348, 2022). "Importantly, upregulation of GRB7 was detected in CRC tissues (from TCGA data) with KRAS mutations, BRAF mutation, and double wild-type genotypes compared to that in normal colon tissues, suggesting an intrinsic function of GRB7 in tumor tissue." (PMID 34718347, 2022). "Therefore, a thorough understanding of the plethora of tumor suppressor miRNAs contributing to KRAS-targeting and its downregulation provides mechanistic insight into discovering potential KRAS-related oncogenic lncRNAs that act as molecular sponges." (PMID 34489556, 2022). "In this study, we found that KRAS-enhanced macropinocytosis could also contribute to an enhanced anti-tumor effect of the dextran conjugate compared to the free drug in KRAS mutant cancer." (PMID 35154474, 2022). "Possibility, KRAS may be considered a genetic diagnosis potential biomarker of multiple malignant neoplastic diseases." (PMID 36330448, 2022). "Additionally, CRC patients with KRAS and NRAS mutations have less favorable prognoses, shorter survival, and increased tumor aggressiveness." (PMID 35723313, 2022). "The abnormal expression of TEAD could modulate several cancer-associated genes, including MYC, KRAS, NF2, BRAF and LKB1, which had crucial roles in the regulation of tumor immunity." (PMID 35077390, 2022). "Besides promoting tumorigenesis through downstream effectors, mutant KRAS cells have been found to interact with the tumor microenvironment." (PMID 35251972, 2022). "This KRAS signature score is indicative of the tumor’s expression of the RAS/MEK/ERK pathway." (PMID 35326598, 2022).
tumor (continued). "Type I tumours are low-grade, more indolent, and less aggressive tumours that are characterized by mutations in mitogen-activated protein kinase (MAPK) regulator pathways (e.g. KRAS or BRAF)." (PMID 35545786, 2022). "While KRAS mutations per se are less frequently observed, GBM shares some common genomic alterations with CRC, like EGFR amplification and WNT activation, which contribute to tumor progression in both primary and recurrent states." (PMID 35664781, 2022). "An experimental study demonstrated that NRF2 activation, in association with a loss in STK11 and KRAS activation, can be associated with a negative prognosis and tumor progression, and can lead to resistance to immunotherapy." (PMID 35406400, 2022). "However, another potential explanation for this discrepancy is the established role of KRAS in facilitating tumor immune escape through downregulation of MHC-I." (PMID 36661655, 2022). "Furthermore, patients with CRC who have a KRAS mutation and MSS/pMMR tumor were part of a group with the poorest prognosis." (PMID 36186777, 2022). "KRAS G12D (26%), G12V (20%), G12C (17%), G13D (6%), and G12A (4%) were the five most common KRASm detected by liquid genotyping, which was similar to the pan-tumor distribution seen in tissue." (PMID 36494601, 2022). "Our data show that intact inflammatory tumor-to-host interactions were required for full KRAS inhibitor efficacy and imply that in vitro drug screens might not be optimal for KRAS inhibitor discovery." (PMID 35327394, 2022). "Based on these findings, we hypothesize that the increase in tumor perimeter found in CAM analyses, may be related to EMT markers caused by the KRAS mutant gene in H292 edited cells." (PMID 35887120, 2022). "In addition, DDX3X promotes KRAS-dependent tumor invasion by activating the β-catenin/ZEB1 pathway that requires β-catenin/TCF4 activation by DDX3X through the Wnt/CK1ε/Dvl2 axis." (PMID 35954483, 2022). "Furthermore, miR-96 showed the downregulation ability of KRAS, resulting in inhibition of cancer cell and tumor growth both in vitro and in vivo." (PMID 35652096, 2022). "Indeed, KRAS mutated tumor cells induced stromal cells to secrete IGF1 and GAS6 that in turn activated IGF1R and AXL signaling in tumor cells, leading to increased mitochondrial performance, proliferative capacity, and resistance to apoptotic stimuli." (PMID 36324182, 2022). "Inhibitors of HSP90 and MEK, when combined, have strong anti-tumor effects in KRAS-mutant lung cancer patient-derived xenograft mouse models and in NSCLC xenograft mouse models, showing a three- to fourfold reduction in tumor weight compared to that of vehicle-treated controls." (PMID 35147163, 2022). "KRAS expression was positively correlated with several clinical and pathological indicators of the tumor progression, including the histological grade, the tumor extent, the nodal status, and the pathological stage (r=0.712, 0.649, 0.646, and 0.865, respectively)." (PMID 36532636, 2022). "In addition, it was functionally confirmed that the signaling cascade induced by the modification of KRAS by ICMT to form the stable TAZ protein supports the ability of tumor cells to self-renew both in vitro and in vivo." (PMID 36430403, 2022). "Evidence already exists showing that women whose tumours contain a KRAS or BRAF mutation have a better outcome than those whose tumours do not carry these MAPK pathway-activating mutations." (PMID 35123694, 2022). "Considering the critical roles of these microRNAs in cancer, such as miR-7-5p and miR-181-5p, we speculate that KRAS may participate in these tumor-relevant mechanisms through microRNA." (PMID 35563733, 2022).
tumor (continued). "Further GSEA analysis showed that in high ZBTB9 expression samples, the G2M checkpoint, epithelial-mesenchymal transition, E2F targets, and KRAS-related signaling pathways were significantly activated, which has been reported to participate in tumor proliferation and progression." (PMID 36522647, 2022). "In addition, this process is dependent on the tumor cell–intrinsic ability to respond to IFNγ, which is regulated by KRAS signaling and contributes to long-term therapeutic efficacy of KRASG12C inhibition." (PMID 35857848, 2022). "Meanwhile, the ORR and DCR in patients with different tumor site (left colon vs. right colon), KRAS status (wide type vs. mutant) and metastatic site (with liver metastasis vs. without liver metastasis) were also analyzed, no statistical differences were found between groups." (PMID 36226061, 2022). "Likewise, combined therapy of RMC-4550 plus MRTX849 resulted in significantly greater anti-tumor efficacy in 4 out of 6 KRAS G12C in vivo models, compared to monotherapy." (PMID 35251972, 2022). "Second, there was a lack of complete data collections regarding functional status (e.g., Karnofsky and ECOG performance status scoring) and gene mutation (e.g., EGFR, KRAS and ALK) that may influence tumor progression." (PMID 35388133, 2022). "Furthermore, HOXA5 methylation was shown to be associated with age, stage, and tumour status, while HOXA6 methylation was linked to age and KRAS mutation." (PMID 35054365, 2022). "Furthermore, ablation of pancreatic acinar cell cyclooxygenase 2 (Cox-2) in KrasG12D/+ mice abrogated the adverse effects induced by HCD, suggesting that diet-induced pancreatic inflammation is critical for promoting oncogenic KRAS-mediated neoplasia." (PMID 35681705, 2022). "With high expression levels of PDL-1 and EGFR on the cell surface plus both BRAF V600E and KRAS G13D existing within its genome, the A375 KRAS G13D mutant isogenic line is an ideal model suited for future studies focused on the tumor microenvironment and integrated combination therapy strategies." (PMID 36358868, 2022). "Similar results were obtained when the second definition of PTL (LS to not include the rectum) was used; Conclusions: KRAS status modifies the association of tumor site with survival." (PMID 35159066, 2022). "However, in both KRAS mutant and KRAS wild type CCA mouse models, MEK inhibitors were able to repress tumor growth, again suggesting that upstream activating mutations do not always predict treatment outcomes." (PMID 35764936, 2022). "However, the inhibition of tumor cell proliferation through the binding interactions between arene Ru(II) complexes and KRAS G-quadruplex DNA is rarely examined." (PMID 35630522, 2022). "Therefore, the combination treatment showed tumor suppression through Akt inhibition, even in KRAS-mutant CRC cells." (PMID 36387129, 2022). "Tumours treated with αEGFR-mAB-P/KRAS-siRNA/P nanostructures had reduced proliferation rates compared to PBS or control-treated tumours as determined by detection of the proliferation marker Ki67 by immunofluorescence and higher apoptosis rates as determined by TUNEL staining." (PMID 35220407, 2022). "In our study, we included a substantial number of tumors with common KRAS mutations (i.e., G12D, G12V, G13D); henceforth, revealing that tumor phospho‐ERK1/2 levels are not dependent on KRAS oncogenic mutations." (PMID 34919787, 2022).